MIR4493 (microRNA 4493)
Synonyms: hsa-mir-4493
Gene: MicroRNA gene on chromosome 11 (123,381,440 to 123,381,512, reverse strand). Ensembl gene ENSG00000265357.
Homologues: Orthologues: chimpanzee MIR4493 (100% identical).